LINC00240 (long independently transcribed non-coding RNA 240)
Synonyms: bA373D17.1; C6orf41; NCRNA00240
Gene: Long non-coding RNA gene on chromosome 6 (26,956,915 to 27,059,749, forward strand). Ensembl gene ENSG00000224843.
Gene Ontology:
Molecular function: triplet codon-amino acid adaptor activity
Biological process: translation
Diseases named in the same sentence as LINC00240 in open-access papers:
LINC00240 is named in the same sentence as 14 diseases in open-access papers, as found by Europe PMC text mining. Sharing a sentence is not in itself a finding about the gene and the disease. The quoted sentences say what the papers report.
gastric cancer (5 papers, 2021 to 2026). A primary or metastatic malignant neoplasm involving the stomach. "Our study, for the first time, indicated that LINC00240 is a novel gastric cancer susceptibility gene transcribed from the GWAS-identified 6p22.1 locus, highlighting the functional impotence of lncRNAs at risk loci during cancer progression." (PMID 37072811, 2023). "LINC00240, for example, is elevated in gastric cancer cells, and its increased levels are linked to a higher TNM stage, more distant and metastatic lymph nodes, with awful health and low chances of illness-free survival." (PMID 36262998, 2022). "High expression of LINC00240 is beneficial to the malignant phenotype of gastric cancer. miRNA molecules are noncoding RNA with a length of 20 to 22 nucleotides." (PMID 41517663, 2026). "To explore how LINC00240 contributing to gastric tumorigenesis, we firstly detected the cellular localization of LINC00240 in gastric cancer cells." (PMID 37072811, 2023). "Intriguingly, silencing of LINC00240 evidently suppressed DDX21 protein expression in gastric cancer cells." (PMID 37072811, 2023). "We found that LINC00240-depletion inhibited lung metastasis of gastric cancer cells; whereas, stabilized LINC00240 overexpression obviously enhanced gastric cancer lung metastases." (PMID 37072811, 2023). "There were significantly higher LINC00240 expression levels in gastric cancer tissues as compared with normal specimens." (PMID 37072811, 2023). "In summary, we revealed the importance of LINC00240 transcribed from the 6p22.1 locus in gastric cancer and uncovered a novel regulatory partnership between LINC00240 and USP10 in controlling ubiquitination of oncogenic protein DDX21." (PMID 37072811, 2023). "Only LINC00240 exhibits the noticeably higher expression in gastric cancer specimens compared with normal tissues and its high expression levels are associated with worse survival of gastric cancer patients." (PMID 37072811, 2023). "Consistently, LINC00240 promotes malignant proliferation, migration and metastasis of gastric cancer cells in vitro and in vivo." (PMID 37072811, 2023). "LINC00240 functions as an oncogene to enhance malignant behaviors of gastric cancer cells in vitro and in vivo." (PMID 37072811, 2023). "LINC00240 exhibits the noticeably higher expression in gastric cancer specimens compared with normal tissues and its high expression levels are associated with worse survival of patients." (PMID 37072811, 2023). "To test if LINC00240 interacts with certain proteins in gastric cancer, we then performed RNA pulldown assays plus mass spectrometry proteomics with the MGC80-3 cell extracts pulled-down by LINC00240." (PMID 37072811, 2023). "The increased expression of LINC00240 has been reported in different cancers, including non-small cell lung cancer, hepatocellular carcinoma cells, cervical cancer, and gastric cancer cell." (PMID 34842045, 2021). "We next investigated if LINC00240 influences the migration and invasion of gastric cancer cells." (PMID 37072811, 2023). "On the contrary, over-expression of DDX21 could enhance cell proliferation of gastric cancer cells with stable silencing of LINC00240 with shRNAs (all P > 0.05)." (PMID 37072811, 2023). "Furthermore, silencing of LINC00240 evidently suppressed DDX21 protein expression in gastric cancer xenografts." (PMID 37072811, 2023). "Together, these data elucidated the oncogenic functions of LINC00240 in gastric cancer." (PMID 37072811, 2023). "Patients with lower LINC00240 expression had prolonged time of PFS or OS compared to ones with high LINC00240 levels, suggesting that LINC00240 might be involve in gastric cancer progression as a novel oncogene." (PMID 37072811, 2023). "We then examined if LINC00240 could regulate metastasis of gastric cancer cells in vivo." (PMID 37072811, 2023). "Interestingly, we found that LINC00240 locates dominantly in nucleus of gastric cancer cells." (PMID 37072811, 2023).
gastric cancer (continued). "Together, these findings suggested that LINC00240 promotes DDX21 stabilization via intensifying interactions between DDX21 and its novel deubiquitinase USP10 in gastric cancer." (PMID 37072811, 2023). "LncRNA CCAT2 promotes gastric cancer proliferation and invasion through regulating the E-cadherin and LATS2.And LINC00240 promotes GC tumorigenesis via a LINC00240/miR-124-3p/DNMT3B axis as an oncogene, so it may be a potential diagnostic biomarker for GC." (PMID 34422902, 2021). "We also found that LINC00240 interacts with oncoprotein DDX21, suppresses its ubiquitination and stabilize the protein via intensifying binding of DDX21 with its novel deubiquitinase USP10, which, thus, leading to disease progression of gastric cancer." (PMID 37072811, 2023). "Silencing of LINC00240 significantly inhibited proliferation of HGC-27 and MGC80-3 cells (all P < 0.001); whereas, ectopic LINC00240 expression markedly promoted viability of gastric cancer cells (both P < 0.01)." (PMID 37072811, 2023). "Moreover, silencing of LINC00240 significantly promoted apoptosis of gastric cancer cells, but did not impact cell cycle of gastric cancer cells." (PMID 37072811, 2023). "Importantly, LINC00240 could interact and stabilize oncoprotein DDX21 via eliminating its ubiquitination by its novel deubiquitinating enzyme USP10, which, thereby, promote gastric cancer progression." (PMID 37072811, 2023). "Importantly, LINC00240 could interact and stabilize oncoprotein DDX21 via eliminating its ubiquitination by its novel deubiquitinating enzyme USP10, which, thereby, promote progression of gastric cancer." (PMID 37072811, 2023).
cervical cancer (2 papers, 2021). A primary or metastatic malignant neoplasm involving the cervix. "The loss of LINC00240 suppressed cervical cancer development through the sponging of miR-124-3p and the overexpression of LINC00240 induced cervical cancer development." (PMID 33422052, 2021). "LINC00240 acts as an oncogene in cervical cancer progression by modulating the miR-124-3p/STAT3/MICA axis." (PMID 33422052, 2021). "The role of LINC00240 has been reported in esophageal squamous cell carcinoma (ESCC) and cervical cancer progression." (PMID 33422052, 2021).
esophageal squamous cell carcinoma (2 papers, 2020 to 2021). Esophageal squamous cell carcinoma (ESCC) is a type of esophageal carcinoma (EC) that can affect any part of the esophagus, but is usually located in the upper or middle third. "The influence of miRNA expression on mRNA–lncRNA crosstalk has been studied in esophageal squamous cell carcinoma (ESCC), comparing two intrinsic subtypes and identifying the “loss” of miR-186-mediated PVT1–mRNA and miR-26b-mediated LINC00240–mRNA crosstalk as driver events of ESCC development." (PMID 33322692, 2020). "The role of LINC00240 has been reported in esophageal squamous cell carcinoma (ESCC)." (PMID 33422052, 2021).
lung adenocarcinoma (2 papers, 2021 to 2022). A carcinoma that arises from the lung and is characterized by the presence of malignant glandular epithelial cells. "We next examined the LINC00240 expression in the TCGA data set of clinical lung cancers including lung adenocarcinoma and lung squamous carcinoma." (PMID 33422052, 2021).
ovarian carcinoma (2 papers, 2024 to 2026). A malignant neoplasm originating from the surface ovarian epithelium. "LINC00240 exhibited varying expression patterns in human ovarian cancer cell lines A2780 and OVCAR-3, while TRL8 was found to be downregulated in these cell lines, contrary to the model predictions." (PMID 39045330, 2024). "Using datasets GSE66957 and the GEPIA database, we assessed LINC00240 expression levels and employed quantitative real-time polymerase chain reaction (qRT-PCR) to evaluate the expression of LINC00240, miR-30c-5p, and P4HA2 in ovarian cancer samples." (PMID 42108519, 2026).
esophageal cancer (1 paper, 2022). A primary or metastatic malignant neoplasm involving the esophagus. "Knocked down LINC00240 inhibited esophageal cancer cells proliferation, lone formation, and invasion." (PMID 36262998, 2022). "According to molecular mechanism studies, endogenous LINC00240 inhibits the buildup and invasion of esophageal cancer cells by combining and modulating the miR-26a-5p expression." (PMID 36262998, 2022). "LINC00240 was discovered to be substantially present in esophageal cancer tissues in the present research." (PMID 36262998, 2022). "LINC00240 expression is elevated in esophageal cancerous tissues, and knocking down LINC00240 decreases esophageal cancer cell proliferation, clone formation, invasion, and migration via miR-26a-5p." (PMID 36262998, 2022). "In the TCGA database, we found that LINC00240 is elevated in esophageal cancer." (PMID 36262998, 2022). "This research observed that LINC00240 is largely present in esophageal cancer cells, and knocking down LINC00240 can strongly ameliorate the cancer cell growth, clone formation, and malignant abilities of esophageal cancer cells." (PMID 36262998, 2022). "In contrast, LINC00240 (shRNA-240) + miR-26a-5p inhibitor group could significantly block the inhibitory effect of knockdown of LINC00240 (shRNA-240) on the migration ability of esophageal cancer cells." (PMID 36262998, 2022). "Further data analysis in the TIMER database supports that the LINC00240 expression may be considerably related to tumor immune infiltration and indicates that LINC00240 might have a significant function in promoting immune escape of tumor cells in the esophageal cancer tumor microenvironment." (PMID 36262998, 2022).
Hypertension (1 paper, 2022). The presence of chronic increased pressure in the systemic arterial system. "In our study, we used LPS to generate the in vivo model, and overexpression of LINC00240 in the in vivo preeclampsia model inhibited the symptoms of preeclampsia including hypertension, proteinuria, and damages to liver and kidney, making LINC00240 a potential therapeutic target for preeclampsia." (PMID 36153499, 2022).
lung carcinoma (1 paper, 2021). "We found that LINC00240 was downregulated in lung cancer cell line after miR-7-5p transfection with an miR-7-5p mimic." (PMID 33422052, 2021). "We showed that LINC00240 was downregulated in a lung cancer cell line after miR-7-5p mimic transfection." (PMID 33422052, 2021).
lymph nodes metastasis (1 paper, 2021). "High expression of LINC00240 was associated with advanced TNM stage, a higher extent of distant metastasis and lymph nodes metastasis, and the poor overall and disease-free survival of the patients." (PMID 34842045, 2021).
preeclampsia (1 paper, 2022). Preeclampsia is a hypertensive disorder of pregnancy that is characterized by new-onset hypertension with proteinuria presenting after 20 weeks of gestation, and depending on mild or severe forms may initially present with severe headache, visual disturbances, and hyperreflexia. "On the basis of previous findings, our studies further shed light on the underlying molecular mechanism of preeclampsia, and to the best of our knowledge, our study is the first to show the roles of LINC00240 in preeclampsia." (PMID 36153499, 2022). "Overexpression of LINC00240 in in vivo preeclampsia model decreased blood pressure, urine protein, liver and kidney damages, increased fetal weight and length, and induced trophoblast function and M2 macrophage polarization." (PMID 36153499, 2022). "Our study is the first to report roles of LINC00240 in preeclampsia using these in vitro trophoblast models (HTR-8/SVneo and JEG-3)." (PMID 36153499, 2022). "Kidney and liver damages were observed in the preeclampsia group compared to the control group, while overexpression of LINC00240 led to less kidney and liver damages compared to the preeclampsia group." (PMID 36153499, 2022). "Decreased LINC00240 and Nrf2 levels and increased miR-155 level were also observed in placenta tissues from the preeclampsia model, and further overexpression of LINC00240 reversed all the changes on LINC00240, miR-155 and Nrf2 expression levels." (PMID 36153499, 2022). "Overexpression of LINC00240 in the preeclampsia rat model significantly inhibited the elevation of blood pressure and urine protein levels and elevated fetal length and weight." (PMID 36153499, 2022). "In placenta samples from 24 clinically diagnosed preeclampsia patients, we found significantly lower LINC00240 and CK7 (a trophoblast marker) expression compared to normal placenta samples." (PMID 36153499, 2022). "Overexpression of LINC00240 in in vitro preeclampsia cell model and in vivo preeclampsia rat model promoted proliferation, migration, invasion, and fusion of placenta trophoblasts and M2 polarization of placenta macrophages." (PMID 36153499, 2022). "LINC00240 could be a potential therapeutic target for preeclampsia." (PMID 36153499, 2022).
cancer (6 papers, 2021 to 2024). A tumor composed of atypical neoplastic, often pleomorphic cells that invade other tissues. "TCGA database showed that LINC00240 expression was increased in cancer tissues compared to adjacent tissues." (PMID 36262998, 2022). "We first performed a pan-cancer analysis through the TCGA database and observed that LINC00240 expression was elevated in most tumor tissues." (PMID 36262998, 2022). "The genomic localization of LARRPM was at the anti-sense strand of LINC00240, which has been reported to play various roles in different cancers." (PMID 36221069, 2022). "XIST, MALAT1, NEAT1, and LINC00240 up-regulated lncRNA were predicted to bind to hsa-mir-124-3p and promoted the proliferation and metastasis of other cancers by modulating hsa-mir-124-3p, but there are no related studies in CCRCC." (PMID 36531222, 2022).
tumor (2 papers, 2022). "To investigate whether LINC00240 mediates the tumor suppressive roles of LARRPM in LUAD, we stably depleted LINC00240 expression in A549 cells with LARRPM stable overexpression." (PMID 36221069, 2022).
LINC00240 also shares sentences with these, for which no sentence is quoted: non-small cell lung carcinoma (2 papers); hepatocellular carcinoma (1).